RNU6-1239P (RNA, U6 small nuclear 1239, pseudogene)
Gene: Small nuclear RNA gene on chromosome 14 (18,978,847 to 18,978,953, forward strand). Ensembl gene ENSG00000212612.
Homologues: Orthologues: chimpanzee U6 (97% identical), chimpanzee U6 (96% identical), macaque U6 (95% identical), chimpanzee U6 (94% identical), macaque U6 (93% identical), guinea pig U6 (77% identical), dog U6 (76% identical), pig U6 (65% identical). Paralogues in human: RNU6-1268P (100% identical), RNU6-816P (100% identical), RNU6-473P (98% identical), RNU6-617P (98% identical), RNU6-848P (98% identical), RNU6-1049P (97% identical), RNU6-127P (97% identical), RNU6-1021P (93% identical), RNU6-286P (93% identical), RNU6-631P (93% identical), RNU6-749P (93% identical), U6 (93% identical), and 1286 more.